RECK (reversion inducing cysteine rich protein with kazal motifs)
Diseases named in the same sentence as RECK in open-access papers (continued):
Sharing a sentence is not in itself a finding about the gene and the disease.
breast carcinoma (continued). "Studies have indicated that there is a positive correlation between RECK expression in tumors and the survival outcome of patients with other types of tumors, including hepatocellular carcinoma, pancreatic cancer, breast cancer and non-small cell lung cancer." (PMID 23833658, 2013). "In this report, we investigated whether TGF-β1 could be a common regulator for MMPs, TIMPs and RECK in human breast cancer cell models." (PMID 22260435, 2012). "In order to analyze whether TGF-β could act as a common regulator of MMPs, TIMPs and RECK in human breast cancer cell models, we investigated whether these cellular models express key members of the TGF-β network." (PMID 22260435, 2012). "For the first time, we have demonstrated that expression of this membrane-associated MMP inhibitor is regulated by TGF-β1 in a breast cancer cell culture model, suggesting that RECK could be involved in the molecular mechanisms of breast cancer progression." (PMID 22260435, 2012). "Here, we proposed a more extensive approach by analyzing the mRNA expression levels of different MMPs (MMP-2, MMP-9 and MMP-14) and MMP inhibitors by qRT-PCR (TIMP-1, TIMP-2 and RECK) in several models (five human breast cancer cell lines, 72 primary breast tumors and 30 adjacent normal tissues)." (PMID 19144199, 2009). "However, our results demonstrate that RECK mRNA expression level is increased during breast cancer progression." (PMID 19144199, 2009). "On the other hand, high expression levels of RECK, a membrane-associated MMP regulator protein, which is able to suppress tumor invasion and metastasis, were associated with better prognosis in several types of tumor, including breast carcinomas." (PMID 19144199, 2009). "In order to determine whether MMPs and their inhibitors are responsible for the different invasive and metastatic capacities displayed by a panel of five human breast cancer cell lines, we analyzed the expression levels of MMPs, TIMPs and RECK by qRT-PCR." (PMID 19144199, 2009). "Here, we propose a more comprehensive approach by analyzing the expression levels of several MMPs (MMP-2, MMP-9 and MMP-14) and MMP inhibitors (TIMP-1, TIMP-2 and RECK) in different models (five human breast cancer cell lines, 72 primary breast tumors and 30 adjacent normal tissues)." (PMID 19144199, 2009). "We analyzed the expression levels of MMP-2, MMP-9 and MMP-14 and their inhibitors (TIMP-1, TIMP-2 and RECK) by quantitative RT-PCR (qRT-PCR) in five human breast cancer cell lines presenting increased invasiveness and metastatic potential, 72 primary breast tumors and 30 adjacent normal tissues." (PMID 19144199, 2009). "Additionally, we performed a functional analysis of RECK in a breast cancer cell model." (PMID 26449734, 2015). "Furthermore, RECK is repressed in brain metastases compared to primary breast cancers." (PMID 25668816, 2015). "However, in breast cancer, the RECK expression profile remains uncertain and controversial." (PMID 26449734, 2015). "Although high expression levels of RECK have already been correlated with a better clinical outcome for several tumor types, its main function, as well as its potential prognostic value for breast cancer patients, remain unclear." (PMID 26449734, 2015). "Thus, induction of RECK gene expression, observed during breast cancer progression, could be a cellular response to enhanced expression and activity of MMPs." (PMID 19144199, 2009). "In fact, several tumor suppressor genes such as CASP3, RECK, FZD6, and NKX2 were strongly downregulated in MDA-MB-231 breast cancer cells and exhibited promoter hypermethylation in the canine TNBC samples." (PMID 32051475, 2020). "TSA exhibits anti-invasive properties through upregulation of RECK, which further inhibits MMP-2 and MMP-9 in a variety of cell lines, including breast cancer cell lines and hepatocytes, amongst other cancer types." (PMID 27506904, 2016).
breast carcinoma (continued). "MiR-96 has been reported to exert an oncogenic effect in non-small cell lung cancer, esophageal cancer, breast cancer, hepatocellular carcinoma, and prostate cancer, respectively by inhibiting the expression of FOXO3, RECK, FOXO3a and FOXO1." (PMID 26582573, 2015). "However, in breast cancer, the RECK expression profile is controversial and remains unclear." (PMID 26449734, 2015). "We then analyzed TIMP-1, TIMP-3 and RECK mRNA expression and focused on the expression of different MMP proteins in stromal fibroblasts to identify a possible role in canine mammary tumors." (PMID 21726449, 2011). "Studies have reported that the programmed cell death receptor 4 (PDCD-4), fatty acid synthase ligand (FasL), PTEN and RhoB genes are related to the proliferative regulation of breast cancer cells and that Maspin, TIMP3 and RECK genes are related to the invasion regulation of breast cancer cells." (PMID 38041032, 2023). "In breast cancer cells, siRNA successfully reduced the expression of the Emi1 gene, and the expression level of the cell proliferation genes PDCD-4, FasL, PTEN and RhoB, along with invasive genes Maspin, TIMP3 and RECK, decreased significantly (P < 0.05)." (PMID 38041032, 2023). "In addition to reducing RSU1, miR-182-5p promotes tumor cell proliferation, invasion and migration by targeting FOXF2, RECK and MTSS1, and the suppression of MTSS1 (MIM) by miR-182 activates RhoA and promotes breast cancer metastasis." (PMID 32751711, 2020). "In this study, we focused on another region of the RECK CpG island (a promoter/exon-1 region) and found an inverse correlation between its methylation and RECK-inducibility by an HDAC inhibitor, MS275, among a panel of breast cancer cell lines (n=15)." (PMID 27058625, 2016). "Although it continues to serve as an invasion and MMP inhibitor in breast cancer, RECK expression analysis is not useful for prognosis of these patients." (PMID 26449734, 2015). "Although mounting evidence supports the potential role of RECK as a molecular marker for cancer prognosis and controller of cellular metastatic capacity, no reports are available unveiling its function in breast cancer." (PMID 22260435, 2012). "Moreover, all analyzed MMPs inhibitor (TIMP-1, TIMP-2 and RECK) are also over-expressed in MDA-MB-435, MDA-MB-231 and Hs578T breast cancer cells." (PMID 19144199, 2009). "RECK is silenced by DNMT3b-mediated promoter methylation in lung cancer cells in which RECK suppresses invasiveness and inversely correlates with lymph node metastasis in NSCLC, PDAC (pancreatic ductal adenocarcinoma), osteosarcoma, esophageal, and breast cancer." (PMID 32806509, 2020). "In highly invasive breasts cancer cells (MDA-MB-231), TGF-β1-treatment increased the expression of RECK at the mRNA level but diminished the RECK protein levels p38 but not ERK1/2 dependent pathways inhibition, blocked the TGF-β1-mediated increase of RECK mRNA expression." (PMID 26247610, 2015). "Taken together, these results support the idea that RECK-inducibility, as predicted by RPM, may be useful in predicting effectiveness of certain drugs, especially those activating RECK expression, in suppressing malignant growth and behaviors of breast cancer cells." (PMID 27058625, 2016). "However, its role in breast cancer remains unclear, since no functional analysis of the RECK gene is yet available for this model." (PMID 22260435, 2012). "RECK expression did not predict any significant differences in OS and DFS among all of the 1040 breast cancer cases analyzed." (PMID 26449734, 2015). "Multivariate Cox regression analysis demonstrated that RECK did not provide independent prognostic information for breast cancer patient survival, strengthening the already reported evidence that this MMP inhibitor is not a relevant biomarker for breast cancer." (PMID 26449734, 2015).
hepatocellular carcinoma (21 papers, 2012 to 2025). A malignant tumor that arises from hepatocytes. "In hepatocellular carcinoma, RECK expression is associated with less vascular invasion, as well as PD-L1 expression." (PMID 38612895, 2024). "A single‐nucleotide polymorphism (SNP) in the RECK promoter (rs10814325; from TT to TC or CC) has been associated with the risks of developing hepatocellular carcinoma and lymph node metastases of oral cancer." (PMID 32730638, 2021). "This study investigates the potential associations of RECK single-nucleotide polymorphisms (SNPs) with hepatocellular carcinoma (HCC) susceptibility and its clinicopathologic characteristics." (PMID 22428065, 2012). "Upregulation of RECK has been reported to be positively associated with immunogenic and hypovascularity status in hepatocellular carcinoma, suggesting that RECK expression may reflect a connection between immunogenic and hypovascularity." (PMID 37904179, 2023). "The evaluation of genotypes among hepatocellular carcinoma (HCC) patients suggested a possible involvement of RECK gene rs11788747 polymorphism in increasing the susceptibility of individuals to HCC." (PMID 32403397, 2020). "The upregulation of RECK protein prevents the migration and invasion of cancer cells in hepatocellular carcinoma by downregulating the downstream protein STAT3 and matrix metalloproteinases like MMP2, MMP9, and MT1-MMP." (PMID 39456564, 2024). "In line with our results, RECK expression was significantly downregulated in several kinds of tumors, such as gallbladder, oral squamous, and ovarian and hepatocellular carcinoma." (PMID 37904179, 2023). "The down-regulation of RECK promoted the proliferation and metastasis of hepatoma cells." (PMID 37268997, 2023). "In detail, published data on the downregulation of RECK expression and liver-related cancer, hepatocellular carcinoma (HCC) and cholangiocarcinoma (CCA), NAFLD progression to NASH and ischemia/reperfusion (I/R) injury have been reviewed, as well as the effects of RECK regulation by inducers." (PMID 38139236, 2023). "Previous research has demonstrated that Sal B may restrain the migration and invasion of hepatocellular carcinoma through RECK/STAT3 signaling." (PMID 35502178, 2022). "In an animal model, the administration of black-tea polyphenon-B significantly reduces the incidence of dimethylaminoazobenzene (DAB)-induced hepatomas as evidenced by modulation of RECK, matrix metalloproteinase (MMP)-2, MMP-9, and the tissue inhibitor of matrix metalloproteinase-2." (PMID 22428065, 2012). "miR-21 is oncogenic miRNA that affects the expression of many cancer-related genes such as PTEN, RECK, TPM1, and PDCD in colorectal, breast, lung, prostate, gastric, hepatocellular carcinoma, and glioblastoma cancers." (PMID 41200944, 2025). "The administration of Polyphenon-B significantly reduced the incidence of DAB-induced hepatomas as evidenced by the modulation of MMP-2, MMP-9, tissue inhibitor of matrix metalloproteinase (TIMP)-2, and RECK as well as angiogenesis." (PMID 38139236, 2023). "As an inhibitor of matrix metalloproteinase, whether the level of reversion-inducing cysteine-rich protein with Kazal motifs (RECK) in hepatocellular carcinoma (HCC) reflects a link between angiogenesis and immunosuppression is still unknown." (PMID 34093791, 2021). "A recent study reported that efficient knockdown of miR-21 by hierarchically tumor-activated nanoCRISPR-Cas13a (CHAIN) restored RECK expression and crippled downstream MMP-2, which undermined cancer proliferation, migration, and invasion in a hepatocellular carcinoma mouse model." (PMID 38612895, 2024). "As we have shown in the previous sections, mortalin promoted the migration and invasion of hepatocellular carcinoma cells via RECK/STAT3 signaling, and Sal B inhibited EMT, the RECK/STAT3 pathway, MMP9/MMP2, and the migration and invasion of hepatocellular carcinoma cells." (PMID 34876128, 2021).
hepatocellular carcinoma (continued). "A research manifested that upregulation of RECK is related to a high ESTIMATEscore, recruitment of more tumor-infiltrating lymphocytes, lower tumor purity and high PD-L1 expression, and might function as an indicator for ICI treatment in hepatocellular carcinoma." (PMID 37904179, 2023).
glioma (18 papers, 2012 to 2024). A benign or malignant brain and spinal cord tumor that arises from glial cells (astrocytes, oligodendrocytes, ependymal cells). "In the current study, we studied the molecular mechanisms for the anticancer activities of DHA in glioma cells and implicated miR-21 and RECK as a target for therapeutic intervention in DHA-induced cancer cell death and invasion." (PMID 28208619, 2017). "They demonstrated that RECK is regulated by MRE from RECK-3′-UTR mediated by the beta-catenin/STAT3/miR-21 circuit in glioma cells." (PMID 38612895, 2024). "Data show that the RECK gene is post-transcriptionally regulated by miR-21, while RECK protein levels are upregulated by miR-21 inhibition in glioma cells." (PMID 38612895, 2024). "For instance, it has been reported that the overexpression of miR-21 negatively regulates RECK gene expression in glioma, nerve injury, osteosarcoma, esophageal squamous cell carcinoma, and colon cancer." (PMID 38612895, 2024). "Results obtained by RT-qPCR and Western blot indicate that RECK mRNA and protein expression are significantly lower in glioma cells than in normal brain tissue." (PMID 38612895, 2024). "For example, exosomes containing miR-21 produced an effective downregulation of the PDCD4 and RECK genes in glioma cell lines." (PMID 35629138, 2022). "A study of engineered exosomes containing miRNA (particularly miR-21) show they effectively downregulated target genes PDCD4 and RECK of the miR-21 in glioma cell lines." (PMID 35205721, 2022). "To further elucidate the significance of RECK in glioma, we calculated the correlation of RECK expression with clinicopathological features of 88 glioma patients and found that highly expressed RECK was closely related to tumor grade of glioma (p = 0.021)." (PMID 28208619, 2017). "In this study, RECK is activated by DHA treatment in glioma cells, corresponding with the observed inhibition of migratory and invasive ability." (PMID 28208619, 2017). "RECK is often down-regulated in various primary epithelial cancers and gliomas, and the down-regulation correlates with poor prognosis." (PMID 24833255, 2014). "miR-21 plays a role in the regulation of cell proliferation, apoptosis and tumor invasiveness by targeting PTEN, PDCD4, and RECK, and has been shown to be involved in gliomas carcinogenesis process." (PMID 22642976, 2012). "In addition, miR-21 promotes glioma invasion by targeting RECK and TIMP3 genes, which are suppressors of malignancy and inhibitors of matrix metalloproteinases." (PMID 27803763, 2016). "Thus, we speculated that RECK might have important implications for the progression of glioma, and these data implied that DHA was a potential therapeutic treatment of glioma." (PMID 28208619, 2017). "It has been shown that miR-21 modulates cell growth, invasion, and apoptosis by targeting RECK in many cancers, such as oral cancer, esophageal cancer, prostate cancer, and glioma, however the relationship between miR-21 and RECK in lung cancer is largely unknown." (PMID 25084400, 2014). "The oncogenic effect of miRNA-21 in human glioma cells is implemented through the suppression of such tumor suppressor genes as TAp63, HNRPK, JMY, TOPORS, RECK, TP53BP2, TIMP3, PDCD4, and TGFBR2/3." (PMID 37033545, 2023). "By applying lentivirual based vectors in U251 glioma cells lines, we probed anti-oncogenic proteins of PDCD4, RECK and PTEN at both protein and mRNA levels for their expression." (PMID 26284486, 2015). "Further, qRT-PCR and Western blot analysis showed CLEC19A overexpression could reduce the expression levels of PI3K, VEGFα, MMP2, and NF-κB and increase PTEN, TIMP3, RECK, and PDCD4 expression levels in glioma cell lines." (PMID 38167030, 2024). "The increase in miR-21 expression may cause the inhibitors of matrix metalloproteinase (MMPs), such as RECK and TIMP3 to decrease, leading to elevated MMPs and an increased invasiveness of glioma tumor cells." (PMID 37509289, 2023).
glioma (continued). "Consequently, we firstly demonstrated that DHA suppresses the metastasis and invasion of glioma cells via up-regulating RECK in glioma cells, implying that DHA is a candidate agent to treat the metastasis and invasion of glioma in the first clinical trials." (PMID 28208619, 2017). "Moreover, western blot analysis showed the RECK protein level was similar with regards to its mRNA in malignant gliomas, lower grade gliomas, and non-tumor brain tissues." (PMID 28208619, 2017). "Furthermore, we validated the RECK mRNA expression by real-time quantitative reverse transcription-PCR (qPCR), and our results showed that the RECK mRNA level was significantly lower in malignant gliomas compared to lower grade gliomas and non-tumor brain tissues." (PMID 28208619, 2017).
lung carcinoma (17 papers, 2012 to 2025). "The direct targeting of RECK by miR200 has been documented in colorectal cancer specimens and cell lines, lung cancer, and bladder cancer." (PMID 39519143, 2024). "A recent study showed that miR-21 enhanced the invasion of lung cancer cells by targeting RECK, a negative regulator of several MMPs." (PMID 32349289, 2020). "Previous reports demonstrated that miR-21 is overexpressed in lung cancer cells in which miR-21 targets RECK and subsequently enhances cell invasion." (PMID 32349289, 2020). "PTEN, PDCD4 or RECK gene was overexpressed in A549 cells, while miR-21-5p was knocked down in MSCs, A549 or H23 lung cancer cells or primary monocytes by miR-21-5p inhibitor transfection." (PMID 30736829, 2019). "For example, upregulation of miR-21 and miR-92b and downregulation of their direct target RECK, an inhibitor of matrix metalloproteases, has been demonstrated in lung cancer and promotes cellular motility and proliferation." (PMID 27588394, 2016). "PTEN and RECK are important regulators of multistep tumorigenesis in lung cancer and newly identified as direct targets of miR-21." (PMID 25084400, 2014). "Note that TSA has been shown to up-regulate RECK via transcriptional activation to inhibit MMP activity in human lung cancer cells." (PMID 22279574, 2012). "RECK suppression via the STAT3/miR-92a axis promotes the invasiveness of lung cancer cells." (PMID 38495494, 2024). "Further, HDAC inhibitors such as TSA can up-regulate RECK via transcriptional activation in CL-1 human lung cancer cells, as well as rescue hypoxia-suppressed RECK expression in the H-Ras-transformed human breast MCF10A and HT1080 human fibrosarcoma cell lines." (PMID 28134767, 2017). "In our study, we evaluated whether miR-21 participates in cell growth, proliferation, invasion, metastasis, and/or apoptosis via regulating PTEN and/or RECK in the regionally-specific lung cancer GSQCLC." (PMID 25084400, 2014). "STAT3 curbs the RECK expression and increases the activity of MMP-2 and MMP-9 in lung cancer cells by up-regulation of miR-92a, promoting the malignant biological behavior of cells." (PMID 34790697, 2021).